RNU6-1124P (RNA, U6 small nuclear 1124, pseudogene)
Gene: Small nuclear RNA gene on chromosome X (42,174,279 to 42,174,385, reverse strand). Ensembl gene ENSG00000206896.
Homologues: Orthologues: chimpanzee U6 (96% identical), rabbit U6 (88% identical), dog U6 (85% identical). Paralogues in human: RNU6-12P (94% identical), RNU6-13P (94% identical), RNU6-25P (94% identical), RNU6-29P (94% identical), RNU6-32P (94% identical), RNU6-41P (94% identical), RNU6-49P (94% identical), RNU6-1 (93% identical), RNU6-17P (93% identical), RNU6-18P (93% identical), RNU6-2 (93% identical), RNU6-338P (93% identical), and 1285 more.